BNIP3 (BCL2 interacting protein 3)
Diseases named in the same sentence as BNIP3 in open-access papers (continued):
Sharing a sentence is not in itself a finding about the gene and the disease.
tumor (229 papers, 2005 to 2026). "TCGA data analyses also revealed a higher BNIP3 expression in head and neck squamous carcinoma patients' tumour samples associated with lower patient survival." (PMID 39945227, 2025). "B-cell lymphoma-2 (Bcl-2)/adenovirus E1B 19 kDa-interacting protein 3 (BNIP3) reportedly apoptosis-inducing effects in tumour cells and is associated with the progression and treatment of multiple tumours." (PMID 37649051, 2023). "Further comprehensive analysis revealed that the expression of BCL2, LEF1, PLK1, and BNIP3 was correlated with tumor mutation burden, microsatellite instability, drug sensitivity, and pathology stage." (PMID 35251139, 2022). "For instance, in a mouse model of mammary tumors, BNIP3 deletion stimulated tumor growth linked with mitochondrial dysfunction, activation of HIF and elevated ROS production." (PMID 35201480, 2021). "In general, in the initiation of carcinogenesis, mitophagy is inhibited through Parkin mutations while during tumor progression, mitophagy is increased via abnormal regulation of BNIP3." (PMID 34282749, 2021). "BNIP3 can promote tumor growth by promoting necrosis and autophagy and is associated with poor prognosis of patients." (PMID 34616431, 2021). "Other engineering approaches to increase anti-tumor efficacy include insertion of a transgene encoding the proapoptotic protein BNiP3 and the angiogenesis inhibitors endostatin and angiostatin to remodel the tumor microenvironment." (PMID 33535479, 2021). "miR-210 protects hypoxic tumour cells from apoptosis by modulating the expression of the pro-apoptotic Bcl-2 family member BNIP3 and the caspase-8-associated protein FLASH." (PMID 32577155, 2020). "The loss of BNIP3 makes mitophagy proceed abnormally and increases mitochondrial ROS levels, which is related with tumor metastasis in TNBC." (PMID 32587855, 2020). "In this study, BNIP3 deletion promoted the tumor growth associated with reduced mitophagy, elevated ROS production, mitochondrial dysfunction, and activation of HIF-1α-dependent genes, including those promoting glycolysis, angiogenesis and metastasis." (PMID 33207677, 2020). "The expression of BNIP3 was associated with increased apoptosis, decreased cellular proliferation, increased Bax and decreased Bcl-2 levels in the tumor tissues." (PMID 28968982, 2017). "Tumor expression of BNIP3 was associated with tumor dedifferentiation (P = 0.0155), whereas stromal expression of BNIP3 was associated with positive marginal status (P = 0.0010)." (PMID 25719198, 2015). "Both Atg5 and BNIP3 knockdown led to larger tumors, implying that BNIP3-mediated autophagy is an important tumor suppressor mechanism in Ras-linked tumors." (PMID 24710477, 2012). "Tumor-specific hypermethylation has also been found in the promoter regions of various tumor suppressors and other tumor-related genes, including BNIP3, DAPK and RASD1, which are associated with prognosis and drug resistance in MM." (PMID 23259664, 2012). "Downregulation of BNIP3 results in the failure of tumor cells to undergo cell death, and is associated with chemoresistance and poorer survival." (PMID 22458929, 2012). "This could further increase the acid concentration in the microenvironment, and the tumor cell itself could become necrotic due to acidosis-activated BNIP3 caused by high [LAin]." (PMID 40171017, 2025). "Given the lack of conclusive data, this study aimed to clarify the role of BNIP3-mediated mitophagy in muscle wasting associated with cancer, testing whether muscle-specific BNIP3 silencing may counteract muscle atrophy in tumor-bearing mice." (PMID 39766033, 2024).
tumor (continued). "Production of mtROS caused by loss of BNIP3 induced cell proliferation and tumor growth, increased gene expression of HIF1α-dependent glycolysis and angiogenesis, suppressed oxidative phosphorylation, suggesting BNIP3 plays an inhibitory role in mammary tumorigenesis." (PMID 37407961, 2023). "However, it is showed that the loss of BNIP3 is involved in tumor proliferation and lymphatic metastasis." (PMID 35783530, 2022). "Furthermore, there is growing evidence that high expression levels of BNIP3 are associated with aggressive cancer behavior in different tumor types, such as breast, colorectal, prostate, and endometrium." (PMID 36291629, 2022). "Furthermore, BNIP3 loss in this type of tumor was associated with increased angiogenesis, glycolytic shift, and metastatic dissemination." (PMID 35201480, 2021). "Additionally, BNIP3 overexpression in ductal carcinoma was found to correlate with a high risk of tumor recurrence and shorter disease-free survival." (PMID 33207677, 2020). "BNIP3 inactivation or suppression has been associated with glioma, as well as pancreatic, breast and prostate cancer, with murine cancer models suggesting a tumour-suppressor function." (PMID 31936236, 2020). "Notably, BNIP3 has contextual pro-death and pro-autophagic roles, which likely underlie the reported cancer type-dependent effects of BNIP3 as tumour-enhancer or tumour-suppressor." (PMID 29707136, 2018). "Increased apoptotic activity in rMV-BNiP3 infected cells suggests that the expression of BNiP3 in infected cells could contribute to anti-tumor activity in association with recombinant measles virus." (PMID 30697531, 2018). "However, expression of BNIP3 in tumor was significantly associated with better prognosis (hazard ration 0.049, P = 0.008)." (PMID 25719198, 2015). "Longer overall survival was associated with high expression of BNIP3 in tumor (p = 0.010)." (PMID 25719198, 2015). "Thus, similar to effects of Parkin deletion, loss of BNIP3 appears to promote tumorigenesis in mouse models consistent with a tumor suppressor function for mitophagy." (PMID 24350057, 2013). "It is noteworthy that because HIF-1 is involved in both survival and apoptosis of tumour cells, abrogation of the apoptotic pathway caused by silencing BNIP3 may enhance HIF-1-induced survival signals within tumours." (PMID 15756280, 2005). "By intersecting tumor-upregulated genes with WGCNA-derived genes, we identified BNIP3 as the only significant prognostic gene associated with poor survival in both the TARGET and GSE21257 cohorts." (PMID 41809731, 2026). "In vivo xenograft experiments demonstrated that MYOF silencing suppressed tumor growth and increased the expression of mitophagy-related proteins BNIP3 and NIX." (PMID 42271528, 2026). "This part of the experiment showed that overexpression of BNIP3 can inhibit tumor growth in vivo and promote the occurrence of autophagy and apoptosis of tumor cells." (PMID 40837014, 2025). "Inhibition of mitophagy arising from the silencing of BNIP3 expression led to a higher level of mitochondrial ROS generation, reduced cancer cell survival, and ultimately, the inhibition of tumour progression and metastasis." (PMID 39945227, 2025). "Under stress conditions such as chemotherapy and radiotherapy, tumor cells can activate mitophagy through pathways such as PINK1/Parkin, BNIP3, or FUNDC1 to counteract the damage caused by drugs and radiation, leading to the development of resistance." (PMID 41551160, 2025). "BCL2/adenovirus E1B interacting protein 3 (BNIP3), as a tumor suppressor, can activate caspase-3 and inhibit Bcl-2 expression." (PMID 40001550, 2025). "The mitophagy receptor BNIP3 also functions as a tumor suppressor in mammary and pancreatic tumorigenesis, illustrating mitophagy’s crucial role in cancer regulation." (PMID 40750884, 2025).
tumor (continued). "Subsequent scRNA-seq analysis of malignant subpopulations (Ost_1 and Cho_2) revealed three key genes (GABARAP, BNIP3, EIF2AK3) consistently overexpressed in tumor cells and linked to poor outcomes." (PMID 41346635, 2025). "Inhibition of mitophagy arising from silencing BNIP3 expression led to higher levels of mitochondrial ROS, reduced cancer cell survival, and ultimately inhibited tumour progression and metastasis." (PMID 39945227, 2025). "Another case is BNIP3, which can competitively bind Bcl-2 and release Beclin1 to promote autophagy and protect tumor cells." (PMID 40761374, 2025). "In NPC, FOXD1 enhances tumor development and gemcitabine resistance by facilitating mitophagy by activating BNIP3 transcription and expression." (PMID 40999468, 2025). "Studies have shown that key proteins involved in autophagy, such as PINK1, Parkin, BNIP3, and NIX, are important intermediates of various physiological processes in cells, and the genes encoding these proteins are tumor suppressor genes that promote apoptosis." (PMID 40837014, 2025). "We observed a significant decrease in the Q score of PTBP2, BNIP3, and Ki-67 in Ptbp2-KO-KCL22 compared to the KCL22-NTC tumor; however, overexpression of BNIP3 in the Ptbp2-KO-KCL22 cells showed a higher Q score." (PMID 40113750, 2025). "Studies have shown that the expression level of BNIP3 in RCC tumor tissues is low, and overexpression of BNIP3 will promote autophagy in RCC cells." (PMID 40837014, 2025). "HIF-1α enhances reliance on anaerobic glycolysis, further increasing LDH levels, and promotes angiogenesis (via VEGF upregulation), inhibits apoptosis (via BNIP3 regulation), and contributes to tumor stemness and invasiveness." (PMID 41229502, 2025). "The mitophagy receptor BNIP3 is highly expressed in various cancers, including BC and EC, and functions as a tumor suppressor gene." (PMID 40564925, 2025). "BNIP3 modulates cancer cell survival by orchestrating cellular responses to stress conditions and inhibiting tumor growth and metastasis." (PMID 39921807, 2025). "Our study underscores the role of PTBP2 in promoting cell proliferation and tumor formation while enhancing autophagy through Bnip3, thereby supporting the role of PTBP2 as an oncogene in CML." (PMID 40113750, 2025). "In vivo, BNIP3 overexpression decreased tumor volume, Ki67 expression, and increased apoptosis and autophagy markers (P<0.01)." (PMID 40837014, 2025). "It regulates key pathways such as AKT/mTOR, cytochrome c/caspase, and SGK1-FOXO3a-BNIP3, influencing tumor cell proliferation, metastasis, apoptosis, and autophagy." (PMID 40259338, 2025). "Although the first method was ineffective in tumor-bearing mice, the adenovirus-based approach significantly reduced BNIP3 levels and moderately increased muscle fiber size, suggesting partial prevention of muscle atrophy." (PMID 39766033, 2024). "Meanwhile, BNIP3 was upregulated in mouse intracerebral tumor tissues upon administration of AAA237." (PMID 38341584, 2024). "Since transcriptome-level analyses are blind to this level of regulation, BNIP3’s role in tumor progression is likely underestimated." (PMID 38177312, 2024). "In contrast, adenovirus-mediated BNIP3 knockdown successfully decreased BNIP3 levels also in tumor hosts." (PMID 39766033, 2024). "Depletion of BNIP3 in multiple cancers inhibits mitochondrial function and promotes tumor progression through various cell death resistance mechanisms." (PMID 36831455, 2023). "BNIP3 overexpression accelerates the death of macrophages and T cells and promotes tumor proliferation and early metastasis." (PMID 37575253, 2023). "The mitophagy receptor BNIP3 exhibits tumor-suppressive effects and significantly inhibits the growth of primary breast tumors in mouse models." (PMID 38067169, 2023).
tumor (continued). "Our data confirm that the tumor inflammatory microenvironment in vivo abnormally activates the Stat3/HIF-1α/BNIP3 signaling pathway in skeletal muscle, leading to excessive mitophagy, which disrupts the body's energy balance and ultimately leads to fatigue." (PMID 36814560, 2023). "The ROC curve in the training set demonstrated that the expression of BNIP3 had satisfactory accuracy for the prediction of tumor metastasis, which was also verified in all cohorts." (PMID 37190333, 2023). "The study demonstrated that FTO targets m6A in the 3′UTR region of the pro-apoptotic BNIP3 mRNA, suggesting FTO as a potential therapeutic target to enhance BNIP3 expression and decrease tumor growth and metastasis." (PMID 37369946, 2023). "YFSJ and its component quercetin can inhibit the overactivation of skeletal muscle mitophagy mediated by the abnormal activation of the Stat3/HIF-1α/BNIP3 signaling pathway induced by the tumor inflammatory microenvironment, thereby alleviating CRF." (PMID 36814560, 2023). "IGF-1 signaling thus couples the induction of mitochondrial biogenesis to basal levels of mitochondrial turnover via Nrf2 and BNIP3, thereby maintaining mitochondrial homeostasis and facilitating tumor progression." (PMID 36835075, 2023). "BNIP3 is well known as a mitophagy receptor that can activate mitophagy to clear damaged mitochondria to inhibit several types of tumor growth." (PMID 36430694, 2022). "Through immunohistochemical staining, it was showed that in tumor tissues, the increase of BNIP3 promoted the expression of Ki67 and Bcl-2 protein, and inhibited Bax protein." (PMID 35783530, 2022). "The inhibition of LINC00461 reduced the expression of BNIP3 protein in tumor tissues, but also inhibited Ki67 and Bcl-2, and increased the level of Bax protein." (PMID 35783530, 2022). "BNIP3 is required for hypoxia-induced autophagy in mouse embryonic fibroblasts (MEFs) and multiple tumor cell lines, while the knockdown of BNIP3 exacerbates cell death during hypoxia." (PMID 36291629, 2022). "The higher the expression level of BNIP3 in some solid tumors, the higher the degree of tumor necrosis, as well as the gradient changes around the necrotic center, which are closely related to the severity of some ischemia-hypoxic regions in solid tumors." (PMID 36675706, 2022). "BNIP3 expression was first investigated in the tumor and normal samples from the TCGA and the Genotype-Tissue Expression (GTEx) projects." (PMID 35912211, 2022). "As described in a recent study, BNIP3 functioned as a tumor suppressor in breast cancer by inducing cell apoptosis." (PMID 35628623, 2022). "The biological functions of BNIP3 in tumor development were further investigated through knockdown experiments in vitro." (PMID 36578780, 2022). "BNIP3 played a tumor-promoting role by regulating autophagy was further explored under hypoxic conditions." (PMID 35200106, 2022). "Our findings partly corroborate a prior report where the elevated BNIP3 was uncovered to increase as the tumor progresses and upon induction of hypoxic conditions." (PMID 35200106, 2022). "LINC00461, miR-411-5p, or BNIP3 was overexpressed or silenced by transfection, and a tumor-bearing nude mice model was constructed to detect their effects on proliferation and apoptosis." (PMID 35783530, 2022). "The xenograft tumor study also showed that MLD treatment significantly increased the protein levels of BNIP3, Bax, and caspase-3, and the TUNEL immunofluorescence was dramatically enhanced in the MLD-treated group." (PMID 36430694, 2022). "Many reports correlated high expression levels of BNIP3 with the aggressive cancer behavior in different tumor types like breast, colorectal, prostate and endometrial." (PMID 35459212, 2022).
tumor (continued). "The results showed that the overexpression of BNIP3 significantly increased tumor volume and quality." (PMID 35783530, 2022). "Conversely, there are still some studies suggesting that BNIP3 can inhibit the apoptosis of tumor cells." (PMID 33795637, 2021). "Intermediate and strong staining scores of Beclin-1, LC-3, BNIP-3, and Parkin were significantly higher in tumor tissues compared to the adjacent matched control." (PMID 34490076, 2021). "Intermediate and strong staining scores of MnSOD, Beclin-1, LC-3, BNIP-3, and Parkin were significantly higher in tumor tissues compared to the adjacent matched control." (PMID 34490076, 2021). "We found that the tumor cells were rescued by receptor-mediated mitophagy involving BNIP3 and BNIP3L proteins." (PMID 34439183, 2021). "Beclin-1, LC-3, BNIP-3, and Parkin were highly scored as weak staining compared to tumor tissues (p < 0.05)." (PMID 34490076, 2021). "In present study, we further explored the protective autophagy mediated by LMP1 through ERK/HIF1α/BNIP3 pathway to promote the radioresistance of tumor cells." (PMID 33795637, 2021). "Here, we analyzed hypoxia-regulated molecules such as HIF1α and BNIP3 that are commonly up-regulated during tumor progression." (PMID 32668709, 2020). "Induction of BNIP3 by HIP‐1 under hypoxia found in various solid tumors was regarded as one of the factors promoting tumor aggressiveness, increasing resistance to therapy and worsening overall patient survival." (PMID 32412667, 2020). "We have found that CD105− tumor xenografts were enriched in expression of BNIP3 protein when compared with the CD105+ tumor xenografts." (PMID 32214151, 2020). "Overexpression of hypoxia responsive protein BNIP3 in cancerous cells is highly controversial as it has been reported to be associated with promoting cell death, and it has tumour suppresser activity, however, it could also enhance aggressive behaviour of tumours such as cell migration." (PMID 32613561, 2020). "Nuclear expression of HIF‐2α was observed in osteoclasts in 26/124 tumours, the presence of which was associated with expression of HIF-regulated BNIP3 and Glut‐1 in osteoclasts within the same tumour." (PMID 33273561, 2020). "Many studies reported that mitophagy-associated molecules PINK1, Parkin, BNIP3, FUNDC1 promote tumor development, and provide targets for therapeutic inhibition in multiple cancers." (PMID 32587855, 2020). "Several research groups have also shown that BNIP3 overexpression is observed in the tumor tissues of about 57% of patients with NSCLC." (PMID 33207677, 2020). "In 4T1 cells, BNIP3 knockdown significantly weakened FTO-accelerated tumor growth and metastasis in a subcutaneous implantation model and tumor metastasis model in Balb/c mice." (PMID 33505967, 2020). "The regulation of BNIP3 during tumor hypoxia is poorly understood and further studies are needed to understand its causal effect." (PMID 30939818, 2019). "On the contrary, in hypoxic tumor cells, the BNIP3 promoter can be hypermethylated, resulting in its silencing regardless of HIF-1α expression." (PMID 30939818, 2019). "Inhibition of SIRT5 expression or activity in tumor cells or in myoblasts was accompanied by a reduction of BNIP3 and mitophagy." (PMID 31210843, 2019). "Conversely, BNIP3 expression is found to reach maximum during severe hypoxia and is observed close to the necrotic tumor areas." (PMID 30754624, 2019). "With high expression of a hypoxia, serial autophagy markers, such as BNIP3, LC3B and ATG5, were found modulated by HIF1α, and these were often associated with aggressive tumor progression phenotype in vivo." (PMID 31700698, 2019). "In a previous study, a rapamycin-sensitive growth advantage in BNIP3-knockdown tumor xenografts was shown, suggesting that BNIP3 inhibits cell growth by suppressing the mTOR pathway." (PMID 30307949, 2018). "Many studies have elucidated the duality of BNiP3's role as a cancer-type dependant tumor repressor or promoter." (PMID 30697531, 2018).